NOTCH3 (notch receptor 3)
Diseases named in the same sentence as NOTCH3 in open-access papers (continued):
Sharing a sentence is not in itself a finding about the gene and the disease.
Stroke (93 papers, 2009 to 2026). Sudden impairment of blood flow to a part of the brain due to occlusion or rupture of an artery to the brain. "Given their high population frequency, these NOTCH3 variants are an important genetic contributor to stroke and vascular dementia worldwide." (PMID 40265482, 2025). "The NOTCH3 score was significantly associated with a higher life‐time risk of stroke (hazard ratio = 1.8, 95% CI = 1.4 to 2.4, p = 3.1 × 10−5, padj = 1.5 × 10−4)." (PMID 40265482, 2025). "We also report the first CADASIL patient who is a compound heterozygote for two known pathogenic cysteine-altering NOTCH3 variants, who presented with a severe early onset of stroke, migraine, and white matter changes." (PMID 41300806, 2025). "This large-scale study highlights the substantial genetic burden of RNF213 and NOTCH3 variants in Koreans, which partially contributes to the high stroke burden in East Asia." (PMID 40982447, 2025). "A retrospective cohort study of 664 CADASIL patients in the Netherlands and Europe and a general population database found that NOTCH3 mutations located in EGFr1–6 (HR-EGFr) were associated with early stroke onset, poor survival, and severe WMH." (PMID 40470487, 2025). "The study discovered that although the NOTCH3 R544C mutation by itself raised the risk of stroke, carriers of the variant were also much more likely to experience stroke due to modifiable vascular risk factors, such as diabetes mellitus and hypertension." (PMID 40863347, 2025). "The impact of the NOTCH3 Arg544Cys (R544C) variation and related vascular risk factors on stroke was investigated in a Taiwanese population study." (PMID 40863347, 2025). "The most common clinical manifestations in patients with NOTCH3 cysteine-sparing mutations are gait disturbance, cognitive impairment and stroke." (PMID 41018180, 2025). "The NOTCH3 score was significantly associated with lifetime stroke probability and small vessel disease neuroimaging outcomes, but not with age." (PMID 40265482, 2025). "NOTCH3 variants in EGFrs 1-6 have been associated with a 13-fold increase in the risk of stroke and vascular dementia compared to control cases, whilst variants in EGFRs 7-34 display a greater than 2-fold risk compared to healthy individuals." (PMID 41300806, 2025). "CADASIL disease severity is highly variable, and cysteine‐altering NOTCH3 variants (NOTCH3cys) are an important contributor to both early‐ and late‐onset stroke and dementia worldwide." (PMID 40265482, 2025). "If conditions permit, multi-gene combination detection, including NOTCH3 and other target genes associated with stroke risk, can be performed." (PMID 39465783, 2024). "The effect of NOTCH3 risk category on incident stroke probability and progression of MSMD and nLV remained significant after correction for multiple testing." (PMID 38713890, 2024). "Regarding the NOTCH3 gene, an analysis of 200,000 cases in the U.K. revealed that NOTCH3 variants are common in the general population and are also susceptibility genes for isolated stroke and vascular dementia." (PMID 38255218, 2024). "The observation that Notch3-ablated mice develop arterial SMC loss and exhibit increased susceptibility to stroke has motivated the view that CADASIL pathology is caused by a loss of NOTCH3 function." (PMID 38386425, 2024). "Clinical stroke attacks were reported in 62.37% (58/93) of patients with NOTCH3 cysteine-sparing mutations." (PMID 39201482, 2024). "Specifically, variants in EGFr 1–6 of NOTCH3 are associated with an earlier onset of stroke and a more significant accumulation of WMHs, indicating a more severe disease progression." (PMID 39201482, 2024). "Two-year incident stroke probability was predicted by NOTCH3 variant risk category (hazard ratio HR-NOTCH3 vs MR-NOTCH3: 4.3, 95% CI 1.4–13.5, p = 0.011) and age (hazard ratio 1.6, 95% CI 1.1–2.4, p = 0.016), but not by sex and CVRFn." (PMID 38713890, 2024).
Stroke (continued). "Compared with 3252 CADASIL patients from 22 studies, the prevalence of stroke was almost the same as in patients with NOTCH3 cysteine-sparing mutations (61.65% vs. 62.37%), and the prevalence of migraine (49.05% vs. 43.48%) as well." (PMID 39201482, 2024). "In a multivariable model, only NOTCH3 risk category and age were predictors of 2-year cumulative stroke probability." (PMID 38713890, 2024). "The existence of certain NOTCH3 variants is also an important risk factor for sporadic stroke in the Taiwan population." (PMID 36580209, 2023). "A representative proband, carrying the homozygous NOTCH3 p.R544C variants, had his first stroke at 42 years old and later had early-onset dementia (Mini-Mental State Examination = 21) at the age of 46." (PMID 36580209, 2023). "We examined the association of NOTCH3 variant position on stroke onset and other clinical features among patients with CADASIL from the United Kingdom." (PMID 35641310, 2022). "Population-attributable fractions showed that 0.21% of strokes and 0.77% of vascular dementias were attributed to NOTCH3 variants." (PMID 36300346, 2022). "During follow-up for a median (IQR) duration of 12.6 years (11.8-13.2), NOTCH3 variants were associated with incident stroke (HR, 2.60; 95% CI, 1.87-3.50; P = 2.2 × 10−7) and vascular dementia (HR, 5.74; 95% CI, 3.02-9.77; P = 4.4 × 10−6)." (PMID 36300346, 2022). "Presence of NOTCH3 variants was associated with a twofold increase in the odds of stroke (OR: 2.33, 95% CI: 1.50 to 3.45, p=0.0004)." (PMID 33712516, 2021). "Herein, we identified a homozygous nonsense mutation in the NOTCH3 gene in 2 affected siblings of a consanguineous SS family with pediatric stroke." (PMID 32980981, 2021). "In conclusion, we propose NOTCH3 null mutations as a genetic cause for SS with childhood-onset stroke." (PMID 32980981, 2021). "Prior studies had further shown that NOTCH3 mutation carriers display WM abnormalities early in the disease that is detectable well before the occurrence of stroke, cognitive impairment, and disability." (PMID 33130454, 2021). "We performed whole-exome sequencing (WES) in 2 affected siblings of a consanguineous family with childhood-onset stroke and identified a homozygous nonsense mutation within the epidermal growth factor repeat (EGFr) 19 of NOTCH3, p.(Arg735Ter)." (PMID 32980981, 2021). "Population attributable fractions showed that 0.26% of stroke and 0.72% vascular dementia in UK Biobank were attributed to the NOTCH3 variants." (PMID 33712516, 2021). "Although the magnitude of risk for a NOTCH3 variant on stroke and vascular dementia partly depends on variant site, modifiers outside the NOTCH3 gene appear to be important." (PMID 33712516, 2021). "All three patients with NOTCH3 mutations had family histories of stroke, and the average patient age was 51.3 years." (PMID 32477100, 2020). "Lacunar infarctions and white matter lesions of the external capsule, along with family history of stroke, can be prognostic factors that suggest the need for further genetic testing for possible underlying NOTCH3 mutations." (PMID 32477100, 2020). "In this study, all three patients with NOTCH3 p.R75P mutations were relatively young and had family histories of stroke." (PMID 32477100, 2020). "Early-onset, non-hypertensive lacunar infarcts and white matter lesions of the external capsule, and a family history of stroke are candidate factors that suggest the need for further genetic testing for underlying NOTCH3 mutations." (PMID 32477100, 2020). "Three studies (1013 cases/1972 controls) of the NOTCH3 rs3815188 polymorphism were meta-analyzed for atherothrombotic stroke risk." (PMID 31288479, 2019). "Dominant and over-dominant models of NOTCH3 rs3815188 polymorphism in atherothrombotic stroke were interpreted from random-effect models as well." (PMID 31288479, 2019).
Stroke (continued). "Three articles consisting of 1013 cases and 1972 controls were meta-analyzed for the association between NOTCH3 rs3815188 polymorphism and atherothrombotic stroke risk." (PMID 31288479, 2019). "Mutations in Notch2 gene induces Down syndrome and Notch3 mutations lead to cardiovascular disorder CADASIL that causes stroke and vascular dementia with degenerative changes in the vascular smooth muscles." (PMID 31770379, 2019). "Four studies (874 cases/2002 controls) of the NOTCH3 rs3815188 polymorphism and three studies of the NOTCH3 rs1043994 (643 cases/1552 controls) polymorphism were meta-analyzed for lacunar stroke risk." (PMID 31288479, 2019). "In literature, homozygosity of NOTCH3 R133C mutation was reported in a 28 year-old stroke patient at the severe end of clinical spectrum whereas R578C homozygous mutation was found in a 65 year-old men with mild phenotype." (PMID 26308724, 2015). "We found that CMBs are common in CADASIL patients with R544C NOTCH3 mutation and the mean number of CMBs was significant higher in patients with symptomatic stroke." (PMID 25692567, 2015). "In our study hypertension was found to be an independent predictor of CMBs in specific brain areas, as well as symptomatic stroke in CADASIL with R544C NOTCH3 mutation." (PMID 25692567, 2015). "NOTCH3 signaling has also been implicated in ischemic stroke and studies suggest that the NOTCH3 protein is a determinant of stroke burden via vascular smooth muscle cells." (PMID 24086431, 2013). "The family history, stroke-like events, and migraines help lead to the correct diagnosis with confirmation of a Notch3 mutation." (PMID 20182571, 2009). "Likewise, the most common NOTCH3 gene variants, as revealed by whole exome sequencing in all our stroke patients, include NOTCH3 rs15174241 (c.4563A > G), NOTCH3 rs15181626 (c.2742A > G), and NOTCH3 rs15192033 (c.606A > G)." (PMID 41379817, 2025). "Although RNF213 and NOTCH3 variants show incomplete penetrance, carriers may have an elevated stroke risk when exposed to environmental factors such as smoking, hypercholesterolemia, and a sedentary lifestyle." (PMID 40982447, 2025). "We establish that (i) NOTCH3ECD aggregation load in skin vessels is associated with neuroimaging outcomes and stroke risk, and (ii) that the average NOTCH3 score of distinct NOTCH3 variants is a predictor of disease severity, contributing to an improved genotype‐based disease prediction." (PMID 40265482, 2025). "For instance, while deleterious variants in KRIT1 and NOTCH3 are well-known causes of intracerebral hemorrhage and strokes, respectively, the recognition of new KRIT1 variants and rare NOTCH3 variants, such as p.R544C for ischemic small vessel disease, highlights the precision of WES." (PMID 39523358, 2024). "The variants of MTHFR (C677T and A1298C) and NOTCH3 p.R544C may influence the stroke severity under specific conditions of PT, creatinine, INR, and BMI, with risk ratios of 4.8 (95% CI 1.53-15.04) and 3.13 (95% CI 1.60-6.11), respectively (Pfisher<.05)." (PMID 38935968, 2024). "We found that the MTHFR and NOTCH3 p.R544C variants may influence stroke severity in patients with specific conditions of PT, creatinine, INR, and BMI." (PMID 38935968, 2024). "In univariate logistic regression, older age (OR = 1.11), male gender (OR = 3.90), less education (OR = 0.86) and history of hypertension (OR = 8.42) were all risk factors associated with the development of clinical symptoms of stroke or cognitive dysfunction in individual carrying NOTCH3 variants." (PMID 38162905, 2024). "In addition, diffusion tensor image analysis along the perivascular space index was a significant risk factor associated with the development of clinical symptoms of stroke or cognitive dysfunction in individuals carrying NOTCH3 variants." (PMID 38162905, 2024).
Stroke (continued). "The presence of a NOTCH3 variant was associated with at least 2-fold higher odds of any stroke (odds ratio [OR], 2.16; 95% CI, 1.67-2.74; P = 3.2 × 10−8), ischemic stroke (OR, 2.65; 95% CI, 1.96-3.50, P = 5.9 × 10−9), and intracerebral hemorrhage (OR, 2.42; 95% CI, 1.23-4.22; P = .01)." (PMID 36300346, 2022). "Cardiovascular risk burden was associated with increased stroke risk in NOTCH3 and HTRA1 carriers." (PMID 36300346, 2022). "Background and Purpose: Cerebral autosomal dominant arteriopathy with subcortical infarcts and leukoencephalopathy caused by mutations in the NOTCH3 gene is a hereditary cerebral small vessel disease, manifesting with stroke, cognitive impairment, and mood disturbances." (PMID 34938255, 2021). "We used whole-exome sequence data from 200 632 participants in UK Biobank to determine the frequency of NOTCH3 variants, and whether they were associated with stroke and dementia." (PMID 33712516, 2021). "In conclusion, our study shows that typical cysteine-changing NOTCH3 variants are common in the general population and these variants are associated with increased risk of both stroke and vascular dementia, and with MRI markers of SVD including WMH and lacunar infarcts." (PMID 33712516, 2021). "Registry-based studies showed that around 2.1 to 2.8% of stroke patients in Taiwan may harbor p.R544C NOTCH3 mutation and harboring the p.R544C resulted in a three-fold increased risk for stroke." (PMID 32321529, 2020). "Furthermore, all three patients with NOTCH3 mutations had family histories of stroke and showed hyperintensity lesions at external capsules and moderate-to-severe white matter lesions." (PMID 32477100, 2020). "It has been revealed that NOTCH3 polymorphisms can maintain the function and integrity of blood vessels, thus, preventing individuals from lacunar stroke and possibly athrothrombotic stroke." (PMID 31288479, 2019). "It is also postulated that having additional NOTCH3 mutation in exon 9 in the proband might be protective against stroke by modifying the NOTCH3 structure; however, this postulation requires further investigations." (PMID 26270344, 2015). "Interestingly, a NOTCH3 mutation was identified in an octogenarian sporadic patient with a minor stroke demonstrating the potential role of NOTCH3 mutations with less severe presentation." (PMID 24086431, 2013). "In conclusion, we show that the NOTCH3 score in skin vessels is directly associated with stroke probability and neuroimaging outcomes in patients with CADASIL, and that the NOTCH3 score may contribute to genotype‐based risk classification for improved disease prediction." (PMID 40265482, 2025). "Interestingly, in multivariable regression, we found that a lower DTI-ALPS index was an independent risk factor for NOTCH3 variant carriers to become symptomatic (i.e. developing stroke or cognitive dysfunction) even after adjusting for age, sex, education years and hypertension." (PMID 38162905, 2024). "Similarly, the highly active chromosome 19 contains genes such as APOE and Notch 3, whose polymorphisms have implications in, respectively, Alzheimer’s disease (AD) and stroke and dementia associated with cerebral autosomal dominant arteriopathy with subcortical infarcts and leukoencephalopathy." (PMID 33805201, 2021). "To determine the ability of CADASIL-related NOTCH3 mutations to promote CH, we focused on the NOTCHC455R mutation, detected in CADASIL patients with early stroke episodes, and employed a CRE-inducible NOTCH3fl-C455R allele." (PMID 39537978, 2025). "Results indicated that HR-EGFr variants show strong associations with severe stroke risk, elevated normalized WMH volume, and excessive NOTCH3 protein aggregation in VSMCs." (PMID 40470487, 2025). "NOTCH3, encoding a mural-cell receptor, is mutated in CADASIL, a monogenic form of cSVD leading to early-onset stroke and dementia." (PMID 41279343, 2025).
Stroke (continued). "A few common examples of monogenetic abrasions that result in stroke are CADASIL (NOTCH-3 gene) and CARASIL (HTRA1)." (PMID 41164024, 2025). "Stereotyped mutations in NOTCH3 drive CADASIL, the leading inherited cause of stroke and vascular dementia." (PMID 39864627, 2025). "CADASIL diagnosis is usually combined with a positive family history of migraine/stroke/dementia, typical white matter changes on MRI findings, and NOTCH3 detection." (PMID 39465783, 2024). "Positive NOTCH3 testing confirmed the diagnosis, leading to the initiation of antiplatelet and statin therapy under the care of both stroke and neurology teams." (PMID 39507177, 2024). "Mutations in neurogenic locus notch homolog protein 3 (NOTCH3) are responsible for this condition, which poses a high risk of dementia and stroke in middle‐aged adults." (PMID 39507230, 2024). "detected only three cases with pathogenic variants in other monogenetic diseases causing stroke (HTRA1, COL4A1) apart from NOTCH3." (PMID 36411388, 2023). "The specialized investigation, genetic testing for CADASIL (NOTCH3 mutation) and MELAS is often conducted in young adult patients with clinical clues compatible with these stroke syndromes." (PMID 37792783, 2023). "To illustrate this concept, we analyzed the phenotypic spectrum associated with all the functional variants in the causal gene NOTCH3 for CADASIL, the most prevalent Mendelian stroke disorder characterized by autosomal dominant inheritance." (PMID 37479695, 2023). "NOTCH3, HTRA1, and COL4A1/2 pathogenic variants in monogenic stroke; Framingham cardiovascular risk; and ischemic stroke polygenic risk." (PMID 36300346, 2022). "We found lesions in the temporal pole on MRI and a family history of stroke in eight of the 10 (80%) patients with vascular Notch3 ECD deposits." (PMID 35775048, 2022). "In this population-based cohort study of 454 756 individuals, NOTCH3, HTRA1, and COL4A1/2 variants causing monogenic cSVD were associated with increased stroke and dementia risk." (PMID 36300346, 2022). "Previous studies have shown that NOTCH3 EGFR 1-6 variants are associated with more severe disease, and our data confirmed this with markedly increased stroke and dementia risk in carriers of EGFR 1-6 variants." (PMID 36300346, 2022). "Cysteine-changing NOTCH3 variants are more common in the general population than expected from CADASIL prevalence and are risk factors for apparently ‘sporadic’ stroke and vascular dementia." (PMID 33712516, 2021). "This demonstrates that genetic variation in the NOTCH3 gene accounts for a much greater proportion of stroke in the general population than previously thought." (PMID 33712516, 2021). "It promotes vascular smooth muscle cell survival and is upregulated by NOTCH3, mutations in which cause CADASIL1, a genetic cause of stroke." (PMID 33206327, 2021). "Age at first stroke, survival and white matter hyperintensity volume were compared between 664 CADASIL patients with either a NOTCH3 EGFr 1–6 pathogenic variant or an EGFr 7–34 pathogenic variant." (PMID 30032161, 2019). "Furthermore, our study identified several novel and common gene variants in stroke patients through WES, including COL4A2, PSEN2, NOTCH3, and RNF2." (PMID 41379817, 2025). "Rare monogenic causes of stroke, such as mutations in NOTCH3 (linked to CADASIL), COL4A1, or HTRA1, may also be found with genetic testing." (PMID 40863347, 2025). "After stratification for NOTCH3 variant risk category, the association between the NOTCH3 score and neuroimaging outcomes and lifetime stroke probability remained significant, but not PVS score." (PMID 40265482, 2025). "Furthermore, we found Notch3 expression in astrocytes across various scRNAseq datasets from neurologic diseases, including aging, LPS‐induced inflammation, stroke, Alzheimer disease, and experimental autoimmune encephalomyelitis (EAE)." (PMID 39853935, 2025).